NF1 (neurofibromin 1)
Diseases named in the same sentence as NF1 in open-access papers (continued):
Sharing a sentence is not in itself a finding about the gene and the disease.
epilepsy (continued). "Further studies are needed to explain the role of NF1 gene and protein in nervous system development and the mechanism of epilepsy." (PMID 40895107, 2025). "The study dose is within the bounds of a typical dose for the treatment of epilepsy in adolescents, with the antiseizure mechanism of lamotrigine being similar to that responsible for improved memory and learning in Nf1 mutant mice." (PMID 39340758, 2025). "Epilepsy is a relatively rare phenotype in NF1, and a recent systematic review reported an estimated lifetime prevalence of epilepsy in NF1 patients of approximately 5.4%, with lower values (<4%) in pediatric patients." (PMID 37993422, 2023). "From the current study, four variants were located in the epilepsy-related genes, the DPYD gene, NF1 gene, and WDR26 gene." (PMID 34055682, 2021). "In addition, we found that only 1.27% of NF1 patients developed seizures in the absence of structural brain abnormalities, arguing against the hypothesis that specific mechanisms, inherent to NF1 and neurofibromin cellular function, may determine an increased risk of epilepsy in this condition." (PMID 34944956, 2021). "Our study aimed to further investigate the correlation between NF1 and epilepsy and to describe clinical features and possible comorbidities in a large cohort of consecutive unselected patients." (PMID 34944956, 2021). "Seizures, epilepsy, and infantile spasms, within the context of NF1, have been related to disruption in the ras/NF1-related MEK/MAPK/ERK signaling pathway." (PMID 32827285, 2020). "Several mutations in participating proteins on this pathway—for example, TSC1/2, RHEB, phosphatase tensin homolog (PTEN), and neurofibromin (NF1)—were described to be implicated with neurological disorders such as ASD, epilepsy, and ADHD85." (PMID 32948744, 2020). "In this group two third of children (6/9 patients) had a family history of seizures or epilepsy that segregated independently of NF1." (PMID 29566708, 2018). "We also report the case of patient 1 who had typical temporal epilepsy; his father was similarly affected by NF1 and epilepsy." (PMID 29566708, 2018). "Recent data from patients with NF1 and seizures show that the increased prevalence of epilepsy in this population is mainly due to intracranial NF1-related tumors." (PMID 29566708, 2018). "Although more and more studies have demonstrated the important role of NF1 protein in neurodevelopment, the specific mechanism of epilepsy susceptibility in NF1 patients has not been fully elucidated." (PMID 40895107, 2025). "If the trafficking of NMDA receptors is increased in NF1, an excitation/inhibition imbalance may occur, resulting in excessive excitation and, in turn, the development of epilepsy." (PMID 40895107, 2025). "Furthermore, 42% of the patients had a first-degree relative with NF1, and approximately a quarter had epilepsy." (PMID 39257551, 2024). "Given that only 3.7% of children with NF1 have epilepsy, that NF1 epilepsy is usually focal, and that the six cases with her NF1 variant did not have seizures, this mosaic variant is unlikely to be contributing to her epilepsy phenotype." (PMID 34717047, 2022). "It is interesting to note that many of the ME-harboring epilepsy-associated genes are typically reported to be dysregulated in TLE patients’ brains, for example, SCN1A, BRD2, and NF1." (PMID 34868252, 2021). "Children with non-structural seizures frequently had a family history of epilepsy, raising questions about the pathogenic role of NF1." (PMID 29566708, 2018). "Linking NF1 to the process of synaptic regulation, 6.5 % of NF1 patients had documented epilepsy." (PMID 26877878, 2016). "Notably, structural lesions cannot account for all cases, as over 50% of NF1-related epilepsy patients lack identifiable structural abnormalities, suggesting that the genetic condition itself may predispose to neuronal hyperexcitability and epileptogenesis." (PMID 40895107, 2025).
epilepsy (continued). "Overall, our results support the hypothesis that the genetic mutation alone may not be sufficient to cause epilepsy in NF1, but that a second-hit from early-life inflammation may be a factor in promoting epileptogenesis." (PMID 38685949, 2024). "Therefore, “second hit” may be one of the pathogenesis of NF1-related epilepsy." (PMID 40895107, 2025). "Importantly, not all patients with NF1-associated epilepsy have focal findings on imaging or EEG, suggesting that genetic mutation alone may predispose to the development of seizure." (PMID 35648241, 2022). "Currently, treatments of signalopathies at the neuronal level are available for NF1 and for ASD with comorbid epilepsy as well as brain cancers." (PMID 34828352, 2021). "This chapter reviews aspects of the clinical presentation and management of epilepsy in TSC, NF1, and SWS and focuses on possible mechanisms of seizures and epilepsy in each disorder." (PMID 28367137, 2017). "Previous reports of NF1-related epilepsy have highlighted the lack of agreement between structural lesions visible on MRI and epileptogenic zones." (PMID 40895107, 2025). "The patient reported here has a family history of epilepsy that did not segregate with the NF1 trait." (PMID 29566708, 2018). "While this finding was used to explain the impaired cognition, learning, and LTP of NF1+/− mice, decreased rather than increased GABA levels would be more consistent with a predisposition to epilepsy." (PMID 28367137, 2017). "By revisiting clinical phenotypes of the three NF1 DNM carriers, we found symptoms compatible with NF1 (e.g. café-au-lait spots) in two patients (carrying c.3445A > G [p.Met1149Val] or c.4835+1G > T variant; both are registered in HGMD with no clear description of epilepsy)." (PMID 31175295, 2019).
acute myeloid leukemia (27 papers, 2010 to 2025). Acute myeloid leukemia (AML) is a group of neoplasms arising from precursor cells committed to the myeloid cell-line differentiation. "In tumors with sporadic NF1 loss, progression-free survival is significantly lower in NF1-deficient individuals compared to other groups for non-small cell lung cancer and acute myeloid leukemia, making NF1 loss a poor prognostic factor." (PMID 39016685, 2024). "Pathogenic variants in the NF1 gene causing Nf1 inactivation have been reported in pediatric acute myeloid leukemia (AML) and T-cell lineage ALL, and are associated with poor prognosis." (PMID 37189588, 2023). "Interestingly, NF1 gene deletions and mutations are frequent oncogenic events in acute myeloid leukemia and MPNST." (PMID 26646588, 2016). "Patients with NF1 are also at increased risk of developing myeloid leukemia and other genotoxin-induced malignancies, and homozygous mutations in NF1 were recently reported in a subset of adult acute myelogenous leukemias (AML)." (PMID 24386979, 2014). "Optic gliomas and malignant peripheral nerve sheath tumors (MPNSTs) are the most frequently observed types of cancer in children with NF1, with a high incidence of acute myeloid leukemia (AML)." (PMID 38893137, 2024). "Constitutional NF1 mutations are known to predispose individuals to myeloid malignancies such as chronic myelomonocytic leukaemia (CMML), JMML and acute myeloid leukaemia (AML)." (PMID 28637487, 2017). "MiR-370 was up-regulated in acute myeloid leukemia and functional analyses showed that miR-370 directly targeted NF1 mRNA." (PMID 26646588, 2016). "Though previous studies have evaluated efficacy of glutaminase inhibitors in cancers such as triple negative breast cancer, acute myeloid leukemia and pancreatic cancer, glutamine dependency in NF1 associated malignancies has not been studied before." (PMID 29212209, 2017). "In a study on acute myeloid leukemia (AML) cells, the results of genome-wide CRISPR/Cas9 screens revealed negative regulators of the MAPK and mTORC1 signaling pathways, including LZTR1, NF1, and TSC1 or TSC2, were associated with sorafenib resistance." (PMID 35715750, 2022). "Of note, mutations in several of the genes that confer leukemia predisposition (e.g., CEBPA, ETV6, GATA2, NF1, RUNX1, PTPN11, CBL, and RAS) are also frequently found in sporadic acute myeloid leukemia (AML) or myelodysplastic syndrome (MDS)." (PMID 29326930, 2017). "In earlier studies, NF1 mutations were reported in up to 7% of acute myeloid leukemia (AML) cases, while 12% of 95 cases studied had copy number alterations in NF1 with mainly heterozygous deletions." (PMID 25026295, 2014). "NF1 mutation, a negative regulator of RAS signaling, has been reported in rare cases of plasma cell myeloma and approximately 4% of acute myeloid leukemia, but not reported in HS." (PMID 29463311, 2018).
Intellectual disability (27 papers, 2007 to 2025). "Taken together, these findings indicatethat intellectual disability is markedly more frequent in patients with type-1NF1 microdeletions as compared to patientswith intragenic NF1 mutations." (PMID 28213670, 2017). "Neurofibromatosis 1 (NF1) is a genetic condition generally associated with intellectual deficiency and learning disabilities." (PMID 24936179, 2014). "Interestingly, two patients (Patients 5 and 16) had full NF1 deletions, which is typically associated with a more severe phenotype, including intellectual disability and a high number of cutaneous neurofibromas." (PMID 32107864, 2020). "Individuals with intragenic NF1 variants who score >1.5–2 SD below the NF1 population mean should be screened for additional variants that may explain the reduced intellectual disability, similar to current guidelines for the general population." (PMID 32015538, 2020). "Intellectual disability is also well described in the NF1 microdeletion phenotype and occurs in over half of patients with the NF1 microdeletion phenotype." (PMID 38596211, 2024). "The high frequency noted in the present study is likely an overestimate due to possible ascertainment bias, it is suspected that individuals with NF1 who have developmental or intellectual disability are more likely to be referred to our local genetic clinics." (PMID 38596211, 2024). "Our cases included children with NF-1 gene mutation who presented with diverse cognitive/developmental dysfunctions including ADHD, ASD, and intellectual disability." (PMID 36419654, 2022). "Several studies havesuggested that intellectual disability occurs disproportionately more frequentlyin NF1 microdeletion patients than in thegeneral NF1 population." (PMID 28213670, 2017). "It is also noteworthy that EHMT targets include fly orthologs of NF1, FMR1, FMR2, CNTNAP2, GDI, DLG3, and of many more genes underlying syndromic and non-syndromic forms of intellectual disability." (PMID 21245904, 2011). "However, 4.8% of the NF1 patients had low-grade, asymptomatic extra-optic brain tumors, and 38.8% had an intellectual disability and/or cognitive impairment." (PMID 36831560, 2023). "Hemizygosity of a gene (or several genes) located within theNF1 microdeletion region may contribute tothe intellectual disability noted in patients with large NF1 deletions." (PMID 28213670, 2017). "Between 3 and 8% of people with NF1 show intellectual disability." (PMID 24936179, 2014). "Since intellectual disability is quite common in patients with mutations of genes encoding PRC2 components, it is likely that the loss of SUZ12 contributes to the cognitive disabilities and severe developmental delay seen in patients with type 1 NF1 deletions hemizygous for SUZ12." (PMID 34681033, 2021). "In addition, many patients with NF1 microdeletions exhibit features which are not usually observed in patients with pathogenic variants within the NF1 gene including facial dysmorphic features, overgrowth, severe global developmental delay and intellectual disability." (PMID 34535841, 2021). "Eight patients had neurological features, including three (none with a full NF1 deletion) who met criteria for intellectual disability, a rare finding in NF1 or LS without a full NF1 deletion." (PMID 32107864, 2020). "NF1 patients carrying substitutions in p.Met1149 presented a milder phenotype with a predominance of skin manifestations, thoracic abnormalities, short stature, macrocephaly, and intellectual disability, with the absence of symptomatic spinal pNFs and OPGs." (PMID 36831560, 2023).
neurocutaneous disorder (27 papers, 2011 to 2025). "NF1, caused by mutations in the NF1 gene on chromosome 17, is a neurocutaneous disorder characterized by benign tumor formation, skin manifestations, and focal areas of signal intensity (FASI) on MRI." (PMID 40951077, 2025). "Neurofibromatosis type 1 (NF1) is a neurocutaneous disorder caused by autosomal dominant germline mutations to the NF1 gene, a tumor suppressor gene on chromosome 17 encoding the protein neurofibromin." (PMID 38685949, 2024). "Neurofibromatosis type 1 (Nf1) is a neurocutaneous disorder caused by an autosomal dominant variant of the NF1 gene, with alteration of its encoded protein product neurofibromin." (PMID 38790247, 2024). "NF1 is a group of heterogeneous multisystem neurocutaneous disorders and is caused by mutations in the NF1 gene, which is considered a classical tumor suppressor." (PMID 26604930, 2015). "Sporadic reports in the literature show that a relationship can exist between a chiefly ectodermal and a primarily mesodermal phakomatosis and NF1 has been reported in association with von Hippel’s disease." (PMID 25424184, 2014). "NF-1 is the most common neurocutaneous syndrome, requiring long-term monitoring for related complications." (PMID 40496547, 2025).
Hypertension (26 papers, 2010 to 2025). The presence of chronic increased pressure in the systemic arterial system. "Previous studies have reported other cardiovascular manifestations secondary to NF1 mutations, including congenital heart diseases, vasculopathy, and hypertension." (PMID 38654147, 2024). "We report on a 9-year-old girl with a novel mutation in NF1 gene and renal artery aneurysm, treated by coil embolization and complicated with hypertension." (PMID 36411470, 2022). "In this study, cardiovascular anomalies associated to NF1 mutations (24/85 patients, 28%) included hypertension, aortic and mitral valves insufficiency, Moyamoya disease (MMS), aortic stenosis, and coarctation of the aorta." (PMID 35885913, 2022). "Hypertension complications or NF-1 itself are both associated with increased cardio-cerebrovascular risk." (PMID 34988040, 2021). "We also summarize the data from previous clinical studies into the hypertension associated with NF-1 to better understand this complication." (PMID 34988040, 2021). "The aim of this study was to investigate NF1 mutations in two Chinese families with NF-1 who presented with early-onset hypertension, and to determine the prevalence of hypertension associated with NF-1 to better understand this complication." (PMID 34988040, 2021). "NF-1 is autosomal dominant disorder and can cause hypertension and renal artery aneurysms that are difficult for surgeries." (PMID 29382000, 2017). "Renal angiography yielded superior diagnostic accuracy in this case and is likely to be a more definitive diagnostic method in patients with NF-1 that present with acute flank pain and hypertension." (PMID 27867667, 2016). "All young patients (<30 years) with hypertension should be clinically screened very early for secondary causes of hypertension, including NF1, so that renal revascularization can be offered before permanent end-organ damage has occurred." (PMID 24678641, 2014). "Furthermore, patients with NF1 germline pathogenic variants exhibited a wide range of clinical features, including a high prevalence of malignant tumors and hypertension." (PMID 39592598, 2024). "Furthermore, by conducting a systematic literature review on patients with NF-1 associated with hypertension, we found that hypertension was a relatively common complication of NF-1, with a prevalence of 6.1–23.4%." (PMID 34988040, 2021). "Early diagnosis and understanding the etiologies of hypertension in patients with NF-1 is a prerequisite for blood pressure control, in avoid of poor outcome including hemorrhagic stroke, retinal arterial microaneurysms, end stage renal disease and so on." (PMID 34988040, 2021). "Routine screening for hypertension in patients with NF-1, especially children and adolescents, is important to avoid serious cardiovascular events." (PMID 34988040, 2021). "We found hypertension was a relatively common complication of NF-1, with a prevalence range of 6.1–23.4%." (PMID 34988040, 2021). "We focused on the prevalence of hypertension and various screen methodology for hypertension in the general NF-1 population." (PMID 34988040, 2021). "Our literature review found six cohorts from seven articles that considered the prevalence of pre-hypertension and hypertension in patients with NF-1; 7.4–22% and 6.1–23.4% for pre-hypertension and hypertension, respectively." (PMID 34988040, 2021). "Patient 1 was a 26-year-old man (proband II-1 in family 1) who was admitted to the Fuwai Hospital with suspected NF-1 and early-onset hypertension." (PMID 34988040, 2021). "Successful endovascular treatment for NF-1 related renal artery aneurysms in adults is reported for the 1st time with preserved renal function and improved hypertension." (PMID 29382000, 2017). "The inherent weakness in vessel wall architecture found in NF1 coupled with the hypertension evident during and after the procedure contributed to haemorrhage and pseudoaneurysm formation." (PMID 23984157, 2013).
Hypertension (continued). "Hypertension was documented in one (out of 16) pregnancies in a female unaffected with NF1 (6.3%)." (PMID 37337089, 2023). "The NF1 patient with vascular fragility in this study had hypertension, which might have been involved in the formation and rupture of de novo aneurysms in a short period." (PMID 34325735, 2021). "Hypertension is a commonly reported finding in adult patients with NF-1 but may also develop during childhood." (PMID 33907652, 2021). "The differences of hypertension prevalence in these studies may be due not only to the different NF-1 populations but also to the different methodologies used to monitor blood pressure." (PMID 34988040, 2021). "Hypertension is not rare in patients with NF-1 for essential or secondary causes." (PMID 34988040, 2021). "Given that the number and location of NF1-related aneurysms are different from non-NF1-related aneurysms and that NF1 aneurysms can be caused without hypertension, the primary etiologies of the LCA aneurysms may be the weakness of vessel wall inherent to NF1." (PMID 30673931, 2019). "In NF-1, PV inactivate the gene and occur in 1 to 5% of the cases, when PPGL is not accompanied by hypertension and in up to 50% of those with hypertension." (PMID 37115176, 2023). "We now report on a 9-year-old girl with NF1 and renal artery aneurysm (RAA), complicated with hypertension." (PMID 36411470, 2022). "Because hypertension is not a rare complication of NF-1, routine screening for hypertension in patients with NF-1, especially children and adolescents, is important to avoid serious cardiovascular events." (PMID 34988040, 2021). "Cardiomyopaties are also described in NF1, with or without the presence of hypertension." (PMID 38739321, 2024). "Hypertension is not a rare complication of NF-1, and it was seen in both probands in this study." (PMID 34988040, 2021). "Interestingly, his first-degree family history revealed no case of hypertension, cardiovascular diseases or NF1." (PMID 24678641, 2014).